ENSG00000287774 (novel transcript)
Gene: Long non-coding RNA gene on chromosome 3 (30,292,448 to 30,305,037, forward strand). Ensembl gene ENSG00000287774.
Gene Ontology:
Biological process: RNA processing
Cellular component: nucleolus